MOGS (mannosyl-oligosaccharide glucosidase)
Description:
In the context of N-glycan degradation, cleaves the distal alpha 1,2-linked glucose residue from the Glc(3)Man(9)GlcNAc(2) oligosaccharide precursor in a highly specific manner.
Synonyms: GCS1; CWH41; DER7; CDG2B
Tractability: Antibody: UniProt predicts a signal peptide or a membrane-spanning region. PROTAC: ubiquitination databases record sites on it; its protein half-life has been measured.
Target class: Enzyme; Hydrolase
Gene: Protein-coding gene on chromosome 2 (74,461,057 to 74,465,410, reverse strand). Ensembl gene ENSG00000115275.
Subcellular location: Endoplasmic reticulum membrane
Subcellular location (Human Protein Atlas): Endoplasmic reticulum
Pathways (Reactome):
Disease: Defective MOGS causes CDG-2b; Maturation of spike protein
Cell-Cell communication: Regulation of CDH1 posttranslational processing and trafficking to plasma membrane
Metabolism of proteins: N-glycan trimming in the ER and Calnexin/Calreticulin cycle
Gene Ontology:
Molecular function: Glc3Man9GlcNAc2 oligosaccharide glucosidase activity; glucosidase activity
Biological process: protein folding; protein N-linked glycosylation; viral protein processing; carbohydrate metabolic process; oligosaccharide metabolic process
Cellular component: endoplasmic reticulum; endoplasmic reticulum membrane; extracellular exosome; membrane
Genetic constraint (gnomAD): Loss-of-function variants: 45 observed, 67.87 expected, observed/expected ratio (o/e) 0.66, 90% interval 0.52 to 0.85. The upper end of that interval is the gene's LOEUF score, 0.85, which puts it in group 3 of 6, group 1 being the genes least tolerant of losing a copy. Missense variants: 1,020 observed, 1,098.5 expected, observed/expected ratio (o/e) 0.93, 90% interval 0.88 to 0.98. Synonymous variants: 492 observed, 456.95 expected, observed/expected ratio (o/e) 1.08, 90% interval 1 to 1.16.
Gene-disease validity (ClinGen):
ClinGen rates the evidence that MOGS causes each of these diseases.
MOGS-congenital disorder of glycosylation (autosomal recessive): Definitive.
Homologues: Orthologues: chimpanzee MOGS (99% identical), macaque MOGS (96% identical), pig MOGS (91% identical), dog MOGS (90% identical), guinea pig MOGS (88% identical), mouse Mogs (86% identical), rat Mogs (85% identical), zebrafish mogs (48% identical), tropical clawed frog mogs (47% identical), Drosophila melanogaster GCS1 (40% identical), Caenorhabditis elegans mogs-1 (34% identical).
Diseases named in the same sentence as MOGS in open-access papers:
MOGS is named in the same sentence as 24 diseases in open-access papers, as found by Europe PMC text mining. Sharing a sentence is not in itself a finding about the gene and the disease. The quoted sentences say what the papers report.
congenital disorder of glycosylation (2 papers, 2021). Congenital disorder of glycosylation (CDG) is a fast growing group of inborn errors of metabolism characterized by defective activity of enzymes that participate in glycosylation (modification of proteins and other macromolecules by adding and processing of oligosaccharide side chains). "A previous study showed that MOGS protein deficiency or MOGS mutation could lead to congenital glycosylation disorders (CDGs), which could lead to retarded development, low immunoglobulin levels, and abnormal liver function." (PMID 33917834, 2021).
antibody deficiency (1 paper, 2024). "ALG12-, ATP6AP1-, and MOGS-CDG fall within as the category of predominantly antibody deficiencies since all of them present hypogammaglobulinemia, with low IgG levels." (PMID 38550576, 2024). "Consequently, this likely contributes to the genesis of the antibody deficiency, inflammatory episodes and absent responses to vaccines observed in ALG12-, MOGS-, and ATP6AP1-CDG." (PMID 38550576, 2024).
colon adenocarcinoma (1 paper, 2023). "Lastly, Western Blot and immunohistochemistry (IHC) were used to identify MOGS expression at the protein level in colon adenocarcinoma tissues." (PMID 37168510, 2023). "MOGS was substantially elevated at the protein level in colon adenocarcinoma as additional confirmation." (PMID 37168510, 2023). "Moreover, we were the first to demonstrate that MOGS is highly expressed in colon adenocarcinoma." (PMID 37168510, 2023).
peripheral nerve injury (1 paper, 2022). Injury to a peripheral nerve. "Consistent with the expression changes of MOGS, the expressions of many metabolism-associated genes, including DDOST, TUSC3, STT3A, STT3B, RPN1, MAGT1, and GANC, were elevated after peripheral nerve injury." (PMID 35575968, 2022).
cancer (3 papers, 2023 to 2025). A tumor composed of atypical neoplastic, often pleomorphic cells that invade other tissues. "Except for MOGS, all six of the prognostic model’s genes have been investigated previously in cancer." (PMID 37168510, 2023). "MOGS, or Mannosyl-Oligosaccharide Glucosidase, was rarely mentioned in cancer research." (PMID 37168510, 2023).
tumor (3 papers, 2023 to 2025). "Based on research into COASY, FTSJ1, and MOGS, this study investigates their associations with immune cell infiltration and the tumor microenvironment, aiming to identify novel targets and strategies for personalized LUAD treatment." (PMID 40313958, 2025). "MOGS, an endoplasmic reticulum glycosidase, exhibits overexpression in tumor cells, which is linked to abnormal glycoprotein modifications and may influence tumor invasiveness." (PMID 40313958, 2025). "MOGS, an important endoplasmic reticulum glycosidase, is often overexpressed in tumor cells, contributing to aberrant glycoprotein modification and tumor malignancy." (PMID 40313958, 2025). "For the first time, we investigated MOGS expression in COAD, and the findings demonstrated that MOGS was substantially more expressed in tumor tissues than in adjacent normal tissues." (PMID 37168510, 2023). "First, we chose 5 pairs of COAD tissues and normal tissues and then used Western Blot to confirm that MOGS was highly expressed in tumor tissues compared to normal tissues at the protein level." (PMID 37168510, 2023). "IHC was then used to show that MOGS was highly expressed in tumor tissues." (PMID 37168510, 2023).
MOGS also shares sentences with these, for which no sentence is quoted: infection (10 papers); malaria (4); viral infections (3); Alzheimer disease (2); Infertility (2); -amyloid (1); colorectal cancer (1); dengue (1); genetic disease (1); Glycosylation disorder (1); hypothyroidism (1); metastasis (1); neurodegenerative disease (1); Parkinson disease (1); protein misfolding diseases (1); rectal cancer (1); Recurrent infections (1); type II diabetes (1).